SYN1 (synapsin I)
Diseases named in the same sentence as SYN1 in open-access papers (continued):
Sharing a sentence is not in itself a finding about the gene and the disease.
depression (26 papers, 2015 to 2026). "Our results showed that BDNF rs6265, PTEN rs12569998, and SYN1 rs1142636 SNP were associated with treatment-resistant depression (TRD)." (PMID 37047730, 2023). "A growing number of studies indicated that alterations of Syn1 were intimately associated with stress-induced depression and that enhancement in Syn1 participates in antidepressant process." (PMID 37308476, 2023). "Downregulation of synaptic genes like Syn1, Rab3a, Camk2a, Nrxn2 have been strongly associated with major depression." (PMID 29743870, 2018). "GATA1 is known to repress transcription of synaptic genes like Syn1, Camk2a, and Rab3a, and associated with Major Depressive Disorder in human patients." (PMID 29743870, 2018). "Growing studies indicated that alteration of SYN1 is intimately associated with stress-induced depression and that enhancement in SYN1 participates in antidepressant process." (PMID 30233424, 2018). "Toxic RNA foci have been demonstrated in astrocytes, cortical neurons and oligodendrocytes in hippocampus, frontal and temporal cortex, thalamus and cerebellum.RAB3A upregulation and synapsin I hyperfosforilation were linked to alteration of long-term potentiation and long-term depression." (PMID 39451985, 2024). "Hypothalamic synaptic plasticity in depression can be caused by increased mRNA expression of synaptotagmin I and synapsin I, and the latter may contribute to depression-like behaviors and HPA axis hyperactivity." (PMID 28246558, 2017). "Synapsin I and PSD-95 are critical for synapse formation and function, with their dysregulation implicated in depression." (PMID 40900922, 2025). "This changed the expression of Syn1 and Bdnf, and, ultimately, circSpna2, leading to depression after TBI." (PMID 39581695, 2024). "Further, the western blot confirmed that p-AKT, p-ERK12, GluA1, p-MEK1, p-MEK2, p-P38, Syn1, and TrkB, which were changed in at least one depression model." (PMID 37308476, 2023). "Based on AKT, MAPK and mTOR signaling pathways, 11 key proteins (AKT/p-AKT, ERK12/p-ERK12, GluA-1, mTOR/p-mTOR, MEK1/p-MEK1, MEK2/p-MEK2, P38/p-P38, P70S6K/ p-P70S6K, PSD95, Syn1 and TrkB) were chosen to be validated by western blot in four depression models." (PMID 37308476, 2023). "We found inconsistent changes in p-ERK12, GluA1, TrkB, Syn1, and p-P38 proteins among the four depression models." (PMID 37308476, 2023). "Findings suggest that the SYN1 gene may play a role in the development of treatment-resistant depression." (PMID 39565757, 2024). "Consistent with the in vitro data, the AAV-mediated overexpression of BAIAP2 in the hippocampus of mice significantly inhibited CMS-induced depression-like behavior, concomitant with increases in dendritic spine density and the expression of GluA1 and SYN1 in hippocampal regions." (PMID 37234209, 2023). "Prolonged stress has been associated with region-specific changes in the expression of BDNF, synaptotagmin I, and synapsin I, and decreased BDNF has been associated with age-related hippocampal dysfunction, memory impairment, and increased risk for depression." (PMID 30429764, 2018). "Those revelations indicate that 5-HT release via synapsin I plays the key role in the depression." (PMID 26927040, 2016). "Several proteins related to neuroplasticity processes have been found to be altered in major depression and animal models of depression, and restored by antidepressant drugs, including mTOR, PSD95, BDNF and synapsin I." (PMID 40405318, 2025). "Eight proteins (p-AKT, p-ERK12, GluA1, p-MEK1, p-MEK2, p-P38, Syn1 and TrkB) in the AKT and MAPK signaling pathways were significantly altered in at least one depression model, while three proteins (p-mTOR, p-P70S6K, PSD95) in the mTOR signaling pathway were not altered." (PMID 37308476, 2023).
depression (continued). "Furthermore, Pearson’s test revealed a potential relationship between the depression-like behavior, the plasma CRP concentration, and the protein expressions of BDNF, Copine 6, synapsin I, or synaptotagmin I in the hippocampus or the PFC." (PMID 30429764, 2018).
autism (15 papers, 2013 to 2025). Persistent deficits in social interaction and communication and interaction as well as a markedly restricted repertoire of activity and interest as well as repetitive patterns of behavior. "Subsequently, an Syn1 nonsense mutation was found to be associated with familial epilepsy, autism, and mental retardation." (PMID 35326282, 2022). "This ‘synaptic autism pathway’ notably includes disruption of SYN1 that is associated with epilepsy, autism and abnormal behavior in both human and mice models." (PMID 23956174, 2014). "Consequently, despite the reduced expression of SYN1 in autism, this could be attributed to the diminished neuronal arborizations associated with autism." (PMID 38994948, 2024). "Moreover, another nonsense mutation in SYN1 (p.W356X), causing mRNA decay, was identified as the cause of epilepsy in a family with the history of syndromic epilepsy associated with behavioral disturbances, learning disabilities and one case of autism." (PMID 23956174, 2014). "This was accompanied by a reduced rate of neuronal growth, bifurcation, network formation, and reduced number of spines and likely synapses as SYN1 expression was reduced by almost 50% in autism." (PMID 38994948, 2024). "Sinapsin-1 (SYN1), a gene specifically expressed in neurons, also exhibited a notable trend toward decreased expression in patients with autism, with a reduction of approximately 50% (p = 0.1, two-tailed t-test)." (PMID 38994948, 2024). "As the child nodes of hub genes, these genes are directly regulated, including known AD-related genes (GABRA1, SYN1, SORSC3, STXBP) and autism risk gene (CHD8)." (PMID 33298176, 2020). "Our study showed that PPA treatment significantly decreased the expression of MMP-9, BDNF, ICAM, Synapsin I, PSD-93, and PSD-95 but elevated GFAP in the brain of PPA-induced PPA-induced autism-like rats." (PMID 35334937, 2022). "Offspring prenatally exposed to VPA showed autism-like behavior, upregulated the levels of LTP and GluN2A, GluA1, and SYN1 proteins relevant to synaptic plasticity in the PFC." (PMID 33994921, 2021). "Synapsin 1 (SYN1), an important presynaptic phosphoprotein and member of a family of proteins involved in synaptic vesicular function was downregulated in cerebellar vermis of adult subjects with idiopathic autism." (PMID 40779003, 2025). "Compared with the control group, the mRNA levels of synaptic development‐related genes SYN1, SYNPO, and axon development‐related genes Lingo‐1 were significantly increased in the VPA‐induced autism model group (p < 0.01) and improved after AVP treatment (p < 0.01)." (PMID 36239083, 2022). "Hence, in addition to SYN1, also SYN2 can participate in the ‘synaptic autism pathway’, implicating the whole Syn family of synaptic genes essential for activity-dependent changes in neuronal function in the pathogenesis of ASD." (PMID 23956174, 2014).
Alzheimer disease (12 papers, 2016 to 2026). A progressive, neurodegenerative disease characterized by loss of function and death of nerve cells in several areas of the brain leading to loss of cognitive function such as memory and language. "Neurodegenerative diseases involve synaptic dysfunction, and synapsin I was significantly decreased in plasma neuronal-derived exosomes of Alzheimer’s disease patients." (PMID 33352833, 2020). "A similar observation was made for synapsin I expression in severe Alzheimer’s disease cortex (Kurbatskayaet al., 2016), whereas expression of other synaptic markers is altered (Honer, 2003;Kurbatskayaet al., 2016)." (PMID 27524794, 2016). "Many of the SNARE complex genes involved in presynaptic vesicle exocytosis were significantly downregulated in Alzheimer’s disease, including SNAP-25, STX1A, SYT1 and VAMP2, while STX2, SYN1 and VAMP3 were not changed." (PMID 34423299, 2021).
Anxiety (9 papers, 2016 to 2025). Intense feelings of nervousness, tension, or panic often arise in response to interpersonal stresses. "In particular, more than a half (four of seven: Cacna2d3, Mapk1, Pomc, and Syn1) of underexpression cases found here associate domestication with anxiety, which is the key trait for mutual trust within a human–pet pair, as demonstrated for dogs, sheep, and guinea pigs." (PMID 31921305, 2019). "In the light/dark box task, anxiety-like behaviors decreased in both Syn1 KI and GFAP KI mice treated with ACTH." (PMID 40015967, 2025). "Consistent with the increased anxiety- and depressive-like behaviors observed in DM mice, Western blot (WB) analysis revealed a significant reduction in the expression of the presynaptic protein synapsin I (SYNI) and the postsynaptic protein PSD95 in the HIP of DM mice compared to CTL mice." (PMID 40244194, 2025). "Interestingly, all three astroglial markers were negatively correlated with anhedonia-like behaviors, while SYN1 and GPHN negatively correlated with anxiety-like behaviors." (PMID 41516045, 2025). "Here, we found that the synaptic marker SYN1 strongly negatively correlated with anxiety- and anhedonia-like behavior, suggesting that unlike astroglial dysfunction, synaptic impairment or loss is involved in both behaviors." (PMID 41516045, 2025). "Anxiety-like phenotypes and abnormal fear learning are observed in mice where CaV1.2 is deleted in glia as well as neurons and in some neuron-specific conditional cKO mouse models, but not in Syn1-Cre neuron-specific conditional knockouts including the work reported here." (PMID 36550186, 2022).
glioma (7 papers, 2019 to 2025). A benign or malignant brain and spinal cord tumor that arises from glial cells (astrocytes, oligodendrocytes, ependymal cells). "Deregulated expression of SYN1 may maintain a cancer stem-like phenotype that contributes to the development of gliomas." (PMID 36193491, 2022). "Additionally, confocal analysis by immunostaining showed that the presynaptic neuronal marker synapsin-1 (SYN-1) could be detected in discrete puncta in the glioma cell-converted neurons, suggestive of synapse-forming neurons." (PMID 31212628, 2019). "For example, REST downregulates synapsin-1 (SYN1), contributing to glioma pathogenesis." (PMID 39602392, 2024). "Among the 10 candidates, high mRNA expression of CCL8, FCGR2B, and TUBA4A and low mRNA expression of GABRD, PRAME, and SYN1 were significantly correlated with worse prognosis, while the mRNA expression of CCL18, SCN1B, SNCB, and VSNL1 showed no connection to the overall survival of glioma patients." (PMID 36685974, 2022).
Parkinson disease (7 papers, 2013 to 2025). A progressive degenerative disorder of the central nervous system characterized by loss of dopamine producing neurons in the substantia nigra and the presence of Lewy bodies in the substantia nigra and locus coeruleus. "Proteomic analyses have identified changes in protein expression associated with Parkinson’s disease, including synaptic proteins like Synapsin I and Synaptophysin, and alterations in autophagy-related proteins." (PMID 40469842, 2025).
schizophrenia (7 papers, 2013 to 2023). A major psychotic disorder characterized by abnormalities in the perception or expression of reality. "SYN1 polymorphism has been previously evaluated in schizophrenia, and the G allele of synonymous SNP (rs1142636, Asn170Asn) in SYN1 was found to be a risk factor for schizophrenia susceptibility in Korean female patients." (PMID 37047730, 2023). "A nonsense mutation in the SYN1 gene was shown to cause familial epilepsy; and some studies have suggested an association of SYN3 with schizophrenia [Reviewed in:]." (PMID 27515700, 2016). "Synapsin I disruption has a marked implication on schizophrenia, which might explain the relationship of CD antibodies with schizophrenia since it promotes the release of neurotransmitters." (PMID 34072914, 2021). "Indeed, group 3 cdDMRs were present in genes such as GRIN1, SYN1, and CAMK2A, and others involved in establishing synapse organization and function, a hallmark of early postnatal brain development, implicating abnormal genetic regulation of neuronal connectivity in schizophrenia development." (PMID 31554518, 2019).
diabetes (6 papers, 2009 to 2025). "In the rat diabetes model established by Kang, the expression levels of synaptic-related proteins PSD95 and SYN1 were also significantly reduced." (PMID 41300164, 2025).
neuroblastoma (6 papers, 2013 to 2024). Neuroblastoma (NB) is the most common solid, extracranial childhood tumor. "In studies carried out in neuroblastoma cell lines, it was observed that Sp1 increases the expression of synapsin I (SYN I), while REST prevents the binding of Sp1, decreasing SYN I." (PMID 38542313, 2024). "Moreover, the simulative effect of nesfatin‐1 on synapsin I through corticotropin‐releasing hormone receptor‐1 is mediated via the cAMP/MAPK/ERK pathway in human neuroblastoma cells." (PMID 38268116, 2024). "Likewise, in neuroblastoma Neuro2a cells, it was recently demonstrated that the transcriptional activator Sp1 directly binds the synapsin I promoter, activating its transcription, and that its activity is directly modulated by the neural master regulator REST." (PMID 27223470, 2016).
Obesity (6 papers, 2018 to 2023). Accumulation of substantial excess body fat. "We previously reported that while there was remarkable anti-obesity phenotype in HFD-fed Syn1-Cre; Ghsrf/f and AgRP-cre; Ghsrf/f mice, the total daily food intake was no different." (PMID 35204795, 2022). "Systemic ablation of ciliary genes from neurons using Syn1-cre led to hyperphagic-induced obesity, and the obesity phenotype of both Kif3a-Syn1-KO and Tg737-Syn1-KO mice was reproduced in POMC-specific Kif3a-KO (Kif3a-Pomc-KO) mice." (PMID 34211092, 2021). "However, the degree of body weight and fat mass decrease in HFD-fed AgRP-cre; Ghsrf/f mice was much less pronounced than that in HFD-fed Syn1-Cre; Ghsrf/f mice, the later has a remarkable anti-obesity phenotype." (PMID 35204795, 2022). "Considering HFD-fed Syn1-cre; Ghsrf/f mice have more pronounced anti-obesity phenotypes than AgRP-cre; Ghsrf/f mice, the distinctive feeding patterns suggest that eating slowly during the optimal feeding period (dark phase for mice) may be beneficial in combating obesity." (PMID 35204795, 2022). "Interestingly, specific deletion of Kif3a or Tg737 using synapsin 1-cre (Syn1-cre) led to similar results of obesity and leptin resistance, indicating that neuronal primary cilia may play important roles in the regulation of body weight homeostasis." (PMID 34211092, 2021). "In our previous studies, we showed that body weight and fat percentage of Syn1-Cre; Ghsrf/f mice were slightly reduced under RD-feeding, but drastically reduced under HFD-feeding, as a matter of fact showing a total prevention of diet-induced obesity." (PMID 35204795, 2022). "Notably, PBMC Syn1 expression appears as an accessible biomarker of cognitive health, reflecting both the detrimental effect of HFD intake at early ages despite the absence of obesity and the positive effects of neonatal leptin treatment on cognition." (PMID 38203399, 2023).
Intellectual disability (5 papers, 2021 to 2025). "Pathogenic SYN1 variants cause intellectual disability (OMIM#300115) or epilepsy with variable learning disabilities and behavior disorders (OMIM#313440)." (PMID 34946860, 2021). "Retrospective examination of SYN1 variants revealed an association between truncating variants and the pathogenicity of REs, and non-truncating variants are more related to developmental delay/intellectual disability (DD/ID)." (PMID 38576531, 2024). "In particular, mutations in the gene encoding SYN1, that we found upregulated in both FAT4 and DCHS1 mutant and KO neurons and hCOs, have been associated with intellectual disability and epilepsy." (PMID 39966398, 2025). "Moreover, it dysregulated other genes linked to intellectual disability, such as FMR1, SYN1, CAMK2A, and THOC2." (PMID 34946860, 2021).
Sepsis (5 papers, 2019 to 2024). Sepsis is defined as life-threatening organ dysfunction caused by a dysregulated host response to infection. "This study shows that higher circulating levels of Syn-1 during the first 7 days of ICU stay are associated with sepsis-related ARDS." (PMID 33726863, 2021). "Glycocalyx degradation as assessed by increased shedding of Syn-1 and hyaluronic acid has been observed in various pathologic states including sepsis, hemorrhagic shock, acute coronary syndrome, volume overload, and surgical and traumatic injury, which have been associated with poor outcome." (PMID 33726863, 2021). "Several studies in sepsis report that SYN-1 is a biomarker of poor outcomes." (PMID 33741039, 2021). "Thus, both SYN-1 and S1P contribute to maintaining vascular barrier integrity, which is severely impaired in sepsis." (PMID 33741039, 2021). "Neither PBR values nor syn-1 levels correlated with any of the microcirculatory parameters in the sepsis cohort." (PMID 31340868, 2019). "The focus on patients with septic shock meant we could not assess the roles played by SYN-1, S1P and VE-cadherin in the progression from severe sepsis to shock." (PMID 33741039, 2021).
cognitive decline (4 papers, 2020 to 2024). "In our previous study involving a MONW animal model with longer exposure to an HFD, we identified Sorl1 and Syn1 as potential indicators of early cognitive decline in PBMCs." (PMID 38203399, 2023). "In correlation with early onset of cognitive decline, we observed significant decrease of cortical synapse markers Syn1 and PSD95 in 2-month-old 5xFAD offspring exposed to antenatal hypoxia, which occurred in somatosensory and prefrontal cortices of 5xFAD mice at 6 months." (PMID 32973487, 2020).
glioblastoma (4 papers, 2019 to 2025). The most malignant astrocytic tumor (WHO grade IV). "We also added U87-MG glioblastoma cells, as Syn-1 has been associated with various neurodegenerative diseases in which various CNS-residing cells (including glial cells) have been potentially implicated." (PMID 38140682, 2023). "RCOR1 may cause deregulated expression of SYN1, which contributes to the maintenance of glioblastoma stem-like cells (GSC)." (PMID 32328342, 2020).
learning disabilities (4 papers, 2021 to 2023). "Additionally, SYN1 mutation is correlated with variable learning disabilities and behavioral disorders (OMIM #300491)." (PMID 34616357, 2021). "It normalizes the levels of BDNF and associated synapsin I and CREB, reduces oxidative damage, and counteracts learning disability." (PMID 36499295, 2022).
Stroke (4 papers, 2020 to 2024). Sudden impairment of blood flow to a part of the brain due to occlusion or rupture of an artery to the brain. "We demonstrated that rats treated with a combination of DBS and MNG increased synaptophysin, synapsin I, and p-synapsin I expressions in the peri-infarct tissue 35 days post-stroke compared with untreated rats." (PMID 39697542, 2024). "The neuronal markers NCAM1 and Syn1 were upregulated, but only the increase in NCAM1 reached significance (**p = 0.0079), indicating that neurons could significantly contribute to the BDEVs pool 72 h after stroke." (PMID 35639208, 2022).